STAT3 (signal transducer and activator of transcription 3)
Diseases named in the same sentence as STAT3 in open-access papers (continued):
Sharing a sentence is not in itself a finding about the gene and the disease.
cancer (continued). "Inflammatory cytokines IL-1 and IL-6 also modulate pro-oncogenic transcription factor STAT3, thereby increasing survival, proliferation, angiogenesis, invasion, and metastasis of cancer cells." (PMID 29370858, 2018). "The JAK/STAT pathway in general and STAT3 in particular play essential pathological roles in multiple cancers including HL." (PMID 29581848, 2018). "STAT3 inhibitor AG490 decreased CD44v6 expression which is regulated by IL-6/STAT3 signaling pathway in cancer cells." (PMID 29747682, 2018). "Next, we evaluated the impact of cancer-derived exosomes on the IL-6/STAT3 signaling pathway in macrophages." (PMID 29867925, 2018). "Signaling is also a potential target, as inhibition of STAT3 signaling reduced arginase activity in myeloid derived suppressor cells from cancer patients." (PMID 29731753, 2018). "The signaling intensity of Rluc therefore indicated the activation of Stat3 signaling in cancer cells." (PMID 30297887, 2018). "Novel therapies are desperately needed, and this has led to investigation of the JAK2/STAT3 pathways, which appear to be play an important role in carcinogenesis of numerous cancers." (PMID 29986501, 2018). "IL-6 is a key downstream target of the STAT3 signaling pathway and we observed an approximately three-fold induction in IL-6 secretion from BMDMs after cancer exosome exposure." (PMID 29867925, 2018). "Like STAT3, p63 acts to transcriptionally regulate a wide variety of genes in cancer that are involved in proliferation, survival and differentiation, and also has major roles in cell adhesion and motility." (PMID 29588647, 2018). "We documented that IL-6 secreted by IR cells activates the JAK2 and STAT3 pathway through IL-6 receptor in cancer cells, leading to the IGF-1Ec upregulation and PEc secretion, as well as to the IL-6 expression and secretion." (PMID 30134795, 2018). "Of these new targets, the signal transducer and activator of transcription 3 (STAT3) has shown to play an important role in the tumorigenesis of many cancer types, including GBM." (PMID 29783757, 2018). "Interleukin 6 (IL-6) is a cytokine secreted by M2 macrophages that promotes cancer cell metastasis by activating signal transducer and activator of transcription 3 (STAT-3) and repressing E-cadherin expression." (PMID 30266897, 2018). "The function of cancer stem cells is modulated by many signaling pathways, including IL-6/STAT3, hedgehog, WNT, and Notch." (PMID 30312311, 2018). "Constitutive activation of STAT3 is predictive of poor prognosis in many types of cancer and although STAT3 is only rarely altered by gene expression changes, mRNA levels show a similar trend." (PMID 29588647, 2018). "T40214 is a G-rich oligodeoxynucleotide selected to target and inhibit the Signal transducer and activator of transcription 3 (STAT3) protein functions in different cancers." (PMID 30274155, 2018). "STAT3 was also known to be upregulated in many cancer patients, and the level of STAT3 was directly correlated with poor prognosis." (PMID 29370858, 2018). "It has been found that cancer cells harboring aberrant STAT3 activity had elevated levels of anti-apoptotic and cell cycle regulating proteins like cyclin D1 and c-Myc." (PMID 29636641, 2018). "In the present study, we found that Wwox affects the IL-6/JAK2/STAT3 (interleukin-6/Janus kinase-2/signal transducer and activator of transcription-3) axis, inhibiting cancer cell growth and metastasis in a STAT3-dependent manner." (PMID 30154439, 2018). "STAT3 is a transcription factor that plays central roles in various physiological processes and its deregulation results in serious diseases including cancer." (PMID 30143645, 2018). "In the present study, we found that the low expression of Wwox is significantly correlated with highly activated STAT3 in basal cancer cells and in TNBC tissues." (PMID 30154439, 2018).
cancer (continued). "STAT3 protein is a key regulator of human cancers, contributing to proliferation, uncontrolled differentiation, survival, invasion, tumorigenesis, and resistance to chemotherapy." (PMID 30186159, 2018). "The active status of myofibroblasts is sustained even in absence of the activating signal, due mainly to the activation of the IL-6/STAT3/NF-κB positive feedback loop that links inflammation to cancer." (PMID 29707149, 2018). "Recently, pre-clinical and clinical studies carried out with STAT3 inhibitors have shown that targeting STAT3 offers a promising therapeutic approach to cancer treatment." (PMID 30400136, 2018). "Accumulating evidence from various studies strongly implicates the role of aberrantly active STAT3 in tumorigenesis, drug resistance, and metastasis of various human cancers including NSCLC." (PMID 29576846, 2018). "In accordance, STAT3 activation via LMP1 induces the expression of mucin 1 cell surface-associated (MUC1), a glycoprotein involved in the early steps of cancer cell detachment." (PMID 29543893, 2018). "Activated STAT3 is observed in a variety of cancer cells, which is a promising therapeutic target to attenuate disease progression." (PMID 30356255, 2018). "Inhibition of STAT3 prevents EMT-associated changes with the overexpression of MCT2 and ZEB1 in EMT-derived cancer cell lines." (PMID 30671168, 2018). "Iontophoretic cancer treatment was used to apply nanocomplex STAT3 siRNA (a small interference RNA) with success in preclinical studies." (PMID 30366360, 2018). "STAT3 plays various roles in many cell types, but it is best known as a regulator of the inflammatory response and of cancer growth." (PMID 30265676, 2018). "STAT3 is found constitutively activated in many human cancers, which is related to malignant characteristics, including rapid proliferation, migration, invasion and metastasis." (PMID 30555277, 2018). "Particularly, the IL-6/JAK/STAT3 autocrine activation loop is a key driver of cancer progression and metastasis in breast cancer." (PMID 29934528, 2018). "The promoters of both Bcl-2 and Bcl-xL contain STAT3 binding sites and can be upregulated by STAT3 in cancer cells." (PMID 30618745, 2018). "Niclosamide confers multiple therapeutic effects for the treatment of cancers, infections, and metabolic diseases by interfering activation of the mTOR, STAT3, and NF-κB signaling pathways." (PMID 30125275, 2018). "Although STAT3 has been shown to play a role in different muscle wasting conditions (e.g., cancer cachexia and auto-immune disorders), only a limited number of studies investigated its role in MD." (PMID 30072615, 2018). "cBioPortal, Kaplan-Meier Plotter, and Prognoscan were performed to identify the prognostic roles of STAT3 in human cancers." (PMID 29423040, 2018). "Here, we will focus on a specific “signal transducer and activator of transcription” (STAT3) factor that is involved in several pathologies, including cancer." (PMID 29843450, 2018). "Hereby, we review the importance and functional complexity of STAT3 signaling in this immune cell compartment as well as potential strategies for cancer therapy." (PMID 29921770, 2018). "More importantly, cancer stem cell subset showed a STAT3 overexpression molecular signature in various tumors." (PMID 30356255, 2018). "For detailed insights into the subject, readers are directed to review articles that outline constitutive STAT3 activation as a common biochemical marker of various cancer types and its targeting by potential chemotherapeutic agents." (PMID 29587429, 2018). "A recent retrospective study found that patients with STAT3 activation in cancer cell-free lymph nodes demonstrated higher rate of metastasis and poorer prognosis, which implicated the possibility of p-STAT3-induced pre-metastatic niches in lymph nodes." (PMID 29795331, 2018). "More in vivo studies are under way to confirm this STAT3-telomerase axis and its role in cancer stem cells." (PMID 30250641, 2018).
cancer (continued). "Signal transducer and activator of transcription 3 (STAT3) is a transcription factor that is latent but constitutively activated in many types of cancers." (PMID 29686295, 2018). "Of particular interest is the development of strategies for STAT3 inhibition, which has been shown to induce apoptotic cell death of STAT3 dependent cancer cells." (PMID 30301213, 2018). "Stat3 is constitutively activated in many human cancers involved in multiple biological functions, such as inflammation, proliferation, oncogenesis, anti-apoptosis progression, and metastasis in cancer." (PMID 30209296, 2018). "We selected several known important proteins in cancer biology, including STAT3, CDC25C, and PLK1, and validated RPPA data by western blotting." (PMID 30221473, 2018). "Stat3 blockade has been shown to inhibit cell proliferation, induce apoptosis, and suppress tumor formation of cancers including lung cancer." (PMID 30209296, 2018). "STAT3 plays a key role in promoting cancer cell survival and proliferation, as well as creating immunosuppressive and thus pro-carcinogenic conditions in the tumor microenvironment (TME)." (PMID 29765155, 2018). "The constitutive activation of STAT3/NFκB signaling can regulate the Notch pathway, which appears to play a key role in a variety of cancers and controls cell fate determination, survival, proliferation, and the maintenance of stem cells." (PMID 29396431, 2018). "An improved understanding of the molecular and cellular targets for cancer treatment, including STAT3, in combination with high-throughput screening, has enabled several opportunities for repurposing drugs for the treatment of cancers." (PMID 29783757, 2018). "As shown in endometrial cancer, IL-6 secreted by CAFs stimulates cancer cell proliferation via the STAT3/c-MYC signaling pathway." (PMID 29883428, 2018). "Since STAT3 plays a key role in survival and growth of cancer cells, we examined the effects of PN on the growth of a panel of human cancer cell lines." (PMID 29921758, 2018). "STAT3 is activated in these EMT-derived cancer cells, which induces aerobic glycolysis and the upregulation of certain enzymes and transporters related to glycolysis (such as MCT2)." (PMID 30671168, 2018). "We have previously shown that STAT3 is regulating telomerase expressions in aggressive cancer cells." (PMID 30250641, 2018). "In conclusion, therapeutic strategies aimed at targeting specific STAT3 interactors are likely to have potential to restrain STAT3-mediated cancer progression with limited detrimental effects on normal cells." (PMID 29914167, 2018). "The proposed therapeutic mechanism of CPS and CRC on cancer cells was reported to inhibit the activation of NF-κB and block the activation of signal transducer and activator of transcription 3 (induced by IL-6)." (PMID 29699594, 2018). "Accordingly, it seems that one of important anticancer effects of DE-EDCP is the reduction of STAT-3 expression in cancer cells." (PMID 29963272, 2018). "Subgroup analyses are ongoing to detect a benefit for patients with high levels of cancer cells expressing STAT3." (PMID 30551640, 2018). "We noted that JAK2/STAT3, TNF-α, mTOR/p70S6K or mTOR/p/0S6K/4E-BP1, and PI3K/Akt/mTOR signaling pathways associated with melittin in cancers were in accordance with the signaling pathway IDs of hsa04630, hsa04668, hsa04150, and hsa04151." (PMID 29854840, 2018). "Signal transducers and activator of transcription (STAT)-3 is activated in cancers, where it promotes growth, inflammation, angiogenesis, and inhibits apoptosis." (PMID 29890775, 2018). "IL-6 has been reported to enhance angiogenesis via the STAT3 pathway to act as a growth factor and to be involved in chemoresistance in cancers." (PMID 29486738, 2018). "As STAT3 is widely considered a signaling molecule with oncogenic properties, it is also considered a good target for anti-cancer therapy." (PMID 30231553, 2018).
cancer (continued). "Although it seems to be an ideal target for anti-cancer therapy, effective approaches to inhibit STAT3 are still missing." (PMID 29588647, 2018). "Among the various functions of the Stat family, Stat3 is involved in the regulation of the self-renewal of embryonic stem cells, cancer stem cells, hematopoietic stem cells and the stem cells in hair follicles." (PMID 30026553, 2018). "In non-cancerous cells, OCIAD2 also interacts with and regulates STAT3 activation and cell migration, which is important in several developmental and immune processes as well as cancer." (PMID 29743632, 2018). "Constitutive activation of Stat3 has been detected at high frequency in diverse human cancer cell lines and tissues." (PMID 29796172, 2018). "Many studies have focused on the control of aberrantly activated STAT3 in cancer cells because it plays important roles in anti-apoptotic and pro-proliferative signaling." (PMID 30400136, 2018). "STAT3 regulated cell survival by inducing Bcl-2 and Bcl-XL to repress apoptosis; thus degradation and inhibition of STAT3 increased apoptosis in several cancer cells." (PMID 30046347, 2018). "Of clinical significance, STAT3 has been reported to be constitutively active in a large number of cancers including haematological malignancies." (PMID 29507689, 2018). "Exogenous STAT3 activation attenuated the cancer stem cell elimination effects of resveratrol treatment." (PMID 30356255, 2018). "RELA (NFκB) is known to be constitutively active in many cancers where it up-regulates anti-apoptotic and other oncogenic genes and here we observe a direct interaction between STAT3 and RELA." (PMID 30143675, 2018). "STAT family of proteins play multiple roles in cancer cells, and specifically, STAT3 has been shown to enhance cancer cell proliferation, migration, and survival, in addition to suppression of antitumor immune response." (PMID 30109213, 2018). "Signal transducer and activator of transcription 3 (STAT3) plays a key role in liver inflammation and cancer." (PMID 29609539, 2018). "This review will provide basic information about STAT3 and its regulation and will focus on its role(s) in stem cells and cancer stem cells." (PMID 29588647, 2018). "This CRAd expressing antisense RNA against signal transducer and activator of transcription 3 (STAT3) was shown capable of depleting STAT3 protein in infected cancer cells, as well as its downstream targets." (PMID 30477117, 2018). "STAT3 is constitutively activated in many cancers; therefore, the mechanisms that regulate STAT3 have been, and continue to be, heavily investigated in order to identify newer and more effective targets for anti-cancer therapies." (PMID 30208623, 2018). "Prx II regulates stemness-associated characteristics of cancers via several pathways, mainly including VEGF/VEGFR/STAT3, Ras/FoxM1, JNK, Wnt/β-Catenin, Hedgehog and androgen (AR)/androgen receptor signaling." (PMID 30177619, 2018). "In cancer cells STAT3 emerged as a as a key regulator of metabolism that integrates signals via both mitochondrial and nuclear activities." (PMID 29765537, 2018). "IL-6 is widely recognized for its crucial role in cancer promoting inflammation, which relies on STAT3 as both survival and tolerogenic signaling." (PMID 29541413, 2018). "Accordingly, the activation of several oncogenes which directly sustain cancer proliferation such as STAT3, NF-κB, and HIF1α are subjected to acetylation." (PMID 29632619, 2018). "Over the years, enhanced and dysregulated STAT3 activity has been observed in a large number of cancer cell lines, indicating this protein as a promising target for the development of anticancer therapies." (PMID 29843450, 2018). "Mechanically, resveratrol treatment decreased cytokines synthesis and inhibited JAK2/STAT3 signaling, which was consistent with the decline of cancer stem cells marker, CD133." (PMID 30356255, 2018).
cancer (continued). "STAT3 is the major inflammation-promoting transcription factor shown to play important roles in cancer progression in various types of tumors." (PMID 30091994, 2018). "In conclusion, we have identified an intriguing feedback loop between cytosolic pH and STAT3 that contributes to the maintenance of alkaline pHc, acidification of lysosomes and transcriptional activity of STAT3 in cancer cells." (PMID 30127373, 2018). "Accumulated studies have provided controversial evidences of prognostic value for signal transducer and activator of transcription proteins 3 (STAT3) in cancers." (PMID 29423040, 2018). "Jab1/CSN5 (c-Jun activation domain-binding protein 1, Jab1 hereafter) was originally identified as a c-Jun coactivator and subsequently discovered to be one of downstream molecules of STAT3, which functions as an oncoprotein in cancers." (PMID 30046347, 2018). "Stattic is known to potently and “selectively” inhibit STAT3 activation and nuclear translocation and selectively induce apoptosis of STAT3 dependent cancer cells." (PMID 29868029, 2018). "Currently, unspecific tyrosine kinase inhibitors (e.g., sorafenib) and monoclonal antibodies (e.g., tocilizumab) that block upstream components in the STAT3 pathway are readily administered to patients as cancer chemotherapeutics." (PMID 29543893, 2018). "Cancer cells with constitutive STAT3 activation have been reported to have elevated levels of cell cycle regulating and anti-apoptotic proteins, leading to resistance to apoptosis." (PMID 29507689, 2018). "Aberrant and persistent activation of the transcription factor STAT3 has been found in various types of cancers." (PMID 30143645, 2018). "Consistently, blockade of STAT3 in cultured cancer cells was found to inhibit cell proliferation, induce apoptosis, and stimulate immune responses." (PMID 29914167, 2018). "Mitochondrial STAT3 sustains altered glycolytic and oxidative phosphorylation activities characteristic of cancer cells, preventing cell death and favouring cell proliferation and metastasis." (PMID 29914167, 2018). "STATTIC as well as STX-0119 have shown to increase the apoptotic rate of a variety of cancer cell lines in vitro and in tumors in vivo, in a STAT3-dependent manner." (PMID 30283459, 2018). "In the A-431 carcinoma cell, platelet-derived growth factor activated STAT3 by using intracellular ROS as a second messenger." (PMID 29541400, 2018). "IL-6 is a pro-inflammatory cytokine, which plays an important role also in the progression and immune-regulation in several types of cancers through the activation of the STAT3 pathway." (PMID 29020964, 2017). "Several members of cucurbitaceae family have been reported to regulate growth of cancer by interfering with STAT3 signaling." (PMID 28598969, 2017). "In human cancer cell lines, an activated STAT3 mutant (STAT3C) increases VEGF expression by binding to VEGF gene promoter." (PMID 28978186, 2017). "Stat3 is present in most human cancer cells and is frequently activated by phosphorylation at Y705, which counteracts pro-apoptotic cascades and stimulate proliferation." (PMID 29133922, 2017). "STAT3 signaling is constitutively activated in various malignant human cancers and participating in multiple cellular progress as well as tumorigenesis." (PMID 28594363, 2017). "Among the STATs, STAT3 is often constitutively actived in various human cancers including mammary of solid carcinoma and hematologic malignancies." (PMID 27861147, 2017). "Reelin contributes to cancer progression by activating integrin β1/Syk/Akt and STAT3 pathways and promoting cell adhesion, survival, proliferation, and drug resistance." (PMID 28345605, 2017). "As an oncogene, in other cancer types, STAT3 has been shown to regulate various aspects of cancer onset and progression including transformation, proliferation, invasion, and metastasis." (PMID 28030809, 2017).